LINC00511 (long independently transcribed non-coding RNA 511)
Synonyms: onco-lncRNA-12; LCAL5; ERRLR01; HI-LNC75; HILNC75; LUCAIR1; RASON; SLNCR; SLNCR1; LINC00673
Gene: Long non-coding RNA gene on chromosome 17 (72,221,072 to 72,640,472, reverse strand). Ensembl gene ENSG00000227036.
Diseases named in the same sentence as LINC00511 in open-access papers:
LINC00511 is named in the same sentence as 56 diseases in open-access papers, as found by Europe PMC text mining. Sharing a sentence is not in itself a finding about the gene and the disease. The quoted sentences say what the papers report.
breast carcinoma (45 papers, 2018 to 2025). "LINC00511 is linked with poor prognosis in breast cancer patients and facilitates the growth of cancer stem cells and tumors." (PMID 35399076, 2022). "Other studies have associated LINC00511 with breast cancer, hepatocellular carcinoma, and bladder carcinoma." (PMID 34771513, 2021). "Thus, elevated expression of LINC00511 is closely linked with clinical pathological features and poor prognosis in breast cancer patients." (PMID 38531930, 2024). "Breast cancer cells had higher LINC00511 expression, which may be associated with proliferation, invasion, and poor prognosis." (PMID 39170516, 2024). "While genetic variations in LINC00511 have been recently detected in Chinese breast cancer patients." (PMID 40790041, 2025). "LINC00511 has a role in the stemness of breast cancer cells since it stimulates the sphere-formation and the expression of stem factors such as Nanog, SOX2, and OCT4 and facilitates CSC features." (PMID 39170516, 2024). "Our research demonstrated that LINC00511 was significantly upregulated in CCA, aligning with other studies that had found increased expression levels of LINC00511 in malignancies such as non‐small‐cell lung cancer, liver cancer, glioma, and breast cancer." (PMID 39445001, 2024). "Expression of LINC00511 in breast cancer samples has been closely correlated with the presence of lymph node metastasis, greater tumor size and molecular subtypes of breast cancer." (PMID 37124625, 2023). "Specifically, LINC00511 has been known to promote the progression of multiple malignancies such as breast cancer, colorectal cancer, lung cancer, hepatocellular carcinoma, and others, making it a promising cancer prognostic molecular marker." (PMID 37888204, 2023). "LINC00511 can also influence the cytotoxic effects of paclitaxel on breast cancer cells through regulating miR-29c/CDK6 axis." (PMID 37124625, 2023). "LINC00511 promotes breast cancer proliferation, migration, and invasion through the miR-150/MMP13 axis." (PMID 37758759, 2023). "We identified the LINC00511/miR-29c-3p axis as the upstream regulatory mechanism of SLC31A1 in breast cancer." (PMID 37275369, 2023). "Another study in breast cancer has revealed more than 180 potential targets for LINC00511 through siRNA and RNA-seq assays." (PMID 37124625, 2023). "In breast cancer, LINC00511 has been found to be highly expressed in the clinical samples and its over-expression has been correlated with poor prognosis." (PMID 37124625, 2023). "Reduced expression of BLACAT1 in HNSCC; MALAT1, NEAT1 and PVT1 in NPC; FAM201A, PVT1 and LINC00857 in NSCLC; LINC00473, CCAT2and Rpph1 in EC; HOTAIR and LINC00958 in CRC; AFAP1-AS1 and LINC00511 in breast cancer were correlated with radiosensitivity." (PMID 36323697, 2022). "The researchers discovered that E2F1 increased Nanog expression at the transcriptional level, suggesting that the LINC00511/E2F1 axis boosted breast cancer stemness and carcinogenesis." (PMID 35790898, 2022). "Linc00511 was found to be enriched in gastric cancer, breast cancer and NSCLC tissues and cell lines and to mediate cell proliferation, invasion, metastasis, and apoptosis." (PMID 35842617, 2022). "It was found that the role of LINC00511 was overexpressed in breast cancer samples, and this overexpression was ascribed to a poor prognosis." (PMID 35790898, 2022). "LncRNA LINC00511 is transcribed from chromosome 17q24.3 region and upregulated in different malignancies, such as glioma, ovarian cancer, breast cancer, cervical cancer, lung cancer, hepatocellular carcinoma, gastric cancer, and renal cell cancer." (PMID 34760707, 2021). "For example, LINC00511 correlates with a poor prognosis in breast cancer, and promotes breast cancer stemness and tumorigenesis via miR-185-3p/E2F1." (PMID 32074085, 2020). "In particular, LINC00511 has been shown to induce radio-resistance in breast cancer resulting in recurrence and progression by regulating STXBP4 expression via miR-185." (PMID 32698787, 2020).
breast carcinoma (continued). "Recent studies found that LINC00511 is overexpressed in various type of cancers including breast cancer, ovarian cancer, liver cancer, pancreatic cancer, lung cancer and glioma." (PMID 32698787, 2020). "In previous studies, LINC00511 was reported to exert an oncogenic function in many cancers, such as breast cancer, non-small cell lung cancer, ovarian cancer and glioma." (PMID 31395854, 2019). "Up to now, LINC00511 has been showed to be overexpressed in many kinds of tumor tissues, and exert oncogenic effects on lung cancer, breast cancer, pancreatic cancer, bladder cancer, osteosarcoma, and tongue squamous cell carcinoma." (PMID 31434692, 2019). "We found that LINC00511 promoted tumour growth by accelerating the G1/S transition and inhibiting apoptosis in breast cancer." (PMID 31395854, 2019). "We determined that high LINC00511 expression was an unfavourable prognostic factor for patients with breast cancer." (PMID 31395854, 2019). "The expression of LINC00511 was further validated by analysing 70 pairs of breast cancer and adjacent normal tissues from the Harbin Medical University Cancer Centre (HMUCC) and RNA-seq data from the TCGA database." (PMID 31395854, 2019). "LINC00511 is also overexpressed in non–small cell lung cancer, pancreatic ductal adenocarcinoma, tongue squamous cell carcinoma, breast cancer, osteosarcoma, glioma, ovarian cancer, and thyroid carcinoma." (PMID 31434797, 2019). "Subsequently, high expression of LINC00511 was further confirmed in lung adenocarcinoma, lung squamous cell carcinoma, breast cancer, pancreatic cancer, bladder cancer, osteosarcoma, and tongue squamous cell carcinoma." (PMID 31434692, 2019). "Results found that LINC00511 functions as a miR-185-3p ‘sponge’ to harbor its expression, and then target E2F1 protein, confirming the role of LINC00511/miR-185-3p/E2F1 axis in breast cancer." (PMID 30482236, 2018). "Further experiments investigated the mechanism by which LINC00511 regulates breast cancer pathophysiology." (PMID 30482236, 2018). "Results show that LINC00511 contributes to the maintenance of breast cancer CSC characteristics, indicating the role of LINC00511 in breast cancer cell stemness." (PMID 30482236, 2018). "Linc00511, a newly discovered oncogenic lncRNA, has found highly expressed in breast cancers, and the silence of linc00511 showed tumor-suppressive functions through inhibiting the proliferation of breast cancer cells." (PMID 30042171, 2018). "This research puts emphasis on the function of LINC00511 on the breast cancer tumourigenesis and stemness, and investigates the in-depth mechanism." (PMID 30482236, 2018). "The role of LINC00511 on the functional phenotype and stemness of breast cancer cells was investigated." (PMID 30482236, 2018). "LINC00511 has been shown as oncogene linked to various cancers as breast and CRC20,25,26 and its genetic variants have been found previously to be associated with breast cancer in the Chinese population." (PMID 40790041, 2025). "LINC00511 binds to the MMP13 protein to promote breast cancer cell migration and proliferation." (PMID 38233788, 2024). "For the stemness and tumorigenesis of breast cancer, the LINC00511/miR-185-3p/E2F1/Nanog axis may possess therapeutic potential." (PMID 39170516, 2024). "Importantly, the LINC00511/miR-29c-3p/SLC31A1 axis was identified as the most potential pathway promoting breast cancer progress by affecting copper transport." (PMID 37275369, 2023). "Our findings, along with existing evidence, suggest that targeting LINC00511 might provide a potential therapeutic avenue for patients with breast cancer." (PMID 35893227, 2022). "LINC00511 is highly expressed in breast cancer and correlated with a poor prognosis." (PMID 34461858, 2021). "LINC00511 was discovered up-regulating in breast cancer 14-16." (PMID 31897240, 2020). "We aimed to provide detailed knowledge of LINC00511 in breast cancer progression." (PMID 31395854, 2019).
breast carcinoma (continued). "The LINC00511/miR-185-3p/E2F1/Nanog axis may have therapeutic potential for breast cancer stemness and tumorigenesis." (PMID 30482236, 2018). "In the present study, results found that lncRNA LINC00511 expression was increased in breast cancer tissue samples and cell lines and may be related to poor prognosis." (PMID 30482236, 2018). "In the present study, LINC00511 acts as an oncogenic RNA in breast cancer tumorigenesis." (PMID 30482236, 2018). "Notably, LINC00511 expression has been increased in early stages of breast cancer." (PMID 37124625, 2023). "The findings revealed that LINC00511 assisted in the preservation of breast cancer CSC features, implying that LINC00511 played a role in breast cancer cell stemness." (PMID 35790898, 2022). "Linc00511 can act as a “sponge” for miR-185-3p, targeting E2F1 and promoting breast cancer tumorigenesis." (PMID 35842617, 2022). "We found that LINC00511 expression was positively correlated with TFAP-2 in cancer cells and breast cancer tissues according to the CCLE and TCGA databases." (PMID 31395854, 2019). "However, the role of LINC00511 in breast cancer tumourigenesis is still unknown." (PMID 30482236, 2018). "Comparison of the lncRNA expression profile in premenopausal fibroids (GSE224991) with estrogen-regulated lncRNAs identified in breast cancer revealed several overlapping transcripts, including MIR503HG, LINC00511, RFPL1S, and CTB-178M22.2, which were upregulated in both datasets." (PMID 40725045, 2025). "Therefore, LINC00511/miR-185-3p/E2F1/Nanog axis has been identified as an important route for induction of stemness and tumorigenesis in breast cancer." (PMID 37124625, 2023). "In turn, LINC00511 could promote expressions of Wnt10A, E2F2, TGFA, and MET and reduce sensitivity of breast cancer cells to Panobinostat." (PMID 37124625, 2023). "Concordant with our findings, LINC00511 was shown to accelerate the G1/S shift and prevent apoptosis in ER-negative breast cancer, and manipulation of LINC00511 expression confirmed a role in tumorigenesis and stemness through miR-185-3p/E2F1/Nanog axis in breast cancer." (PMID 35893227, 2022). "The microRNA and its target were important regulatory mechanism for LINC00511, such as miR-185-3p/E2F1 in breast cancer, miR29b-3p/VEGFA in pancreatic cancer, miR-15a-3p/Wnt signaling pathway in bladder cancer, miR-765/APE1 in osteosarcoma and miR-765/LAMC2 in tongue cancer." (PMID 31434692, 2019). "Results of gain and loss-of-functional assays revealed that LINC00511 promotes sphere-formation, stem factor (Oct4, Nanog, SOX2) expression, and contributes to the maintenance of breast cancer CSC characteristic, indicating the role of LINC00511 in breast cancer cell stemness." (PMID 30482236, 2018). "Similarly, we found that E2F1 mRNA expression was increased in breast cancer cells MDA-MB-231, and MCF-7 and up-regulated in the miR-185-3p inhibitor transfection and enhanced LINC00511 plasmid transfection." (PMID 30482236, 2018). "The results showed that five lncRNAs including HOTAIR, DANCR, PVT1, LINC00511, and NEAT1 and 16 miRNAs and five of their targets—VEGFA, BTG2, E2F3, IRAK1, and SMAD4—have significantly different expression patterns in normal individuals compared to those with breast cancer." (PMID 36726376, 2023).
melanoma (25 papers, 2017 to 2025). A malignant, usually aggressive tumor composed of atypical, neoplastic melanocytes. "Loss of LINC00511 decreased cell viability, reduced proliferation, invasion, and migration of melanoma." (PMID 36874361, 2023). "Loss of LINC00511 inhibited proliferation, metastasis, and epithelial–mesenchymal transition of melanoma through the increase of miR-610 and the decrease of NUCB2." (PMID 36874361, 2023). "Silence of LINC00511 increased miR-610 in melanoma cells, and inhibition of miR-610 attenuated LINC00511 deficiency-induced decrease of cell viability, migration, and invasion of melanoma, suggesting that LINC00511 might contribute to melanoma progression through downregulation of miR-610." (PMID 36874361, 2023). "However, whether over-expression of NUCB2 could reverse the suppressive effect of LINC00511 deficiency on melanoma progression should be investigated in further research." (PMID 36874361, 2023). "Silence of LINC00511 reduced expression of NUCB2 in melanoma cells, and inhibition of miR-610 attenuated LINC00511 deficiency-induced decrease of NUCB2." (PMID 36874361, 2023). "MiR-625-5p was the target of LINC00511 in melanoma cells, and depletion of LINC00511 enhanced the transcript level of miR-625-5p and inhibited glycolysis." (PMID 36874361, 2023). "In conclusion, silence of LINC00511 reduced cell proliferation and metastasis of melanoma through down-regulation of miR-610-mediated NUCB2." (PMID 36874361, 2023). "Our results also identified the upregulation of LINC00511 in melanoma tissues and cells." (PMID 36874361, 2023). "Furthermore, LINC00511 was also elevated in melanoma cells compared to HEMa-LP." (PMID 36874361, 2023). "Therefore, LINC00511 might contribute to melanoma progression through downregulation of miR-610." (PMID 36874361, 2023). "However, the role of LINC00511 in the metastasis of melanoma remains unclear." (PMID 36874361, 2023). "Together, these data demonstrate that expression of LINC00511 in melanoma regulates the miR-625-5p/PKM2 axis, which may explain LINC00511-dependent changes to OCR in A2058 melanoma cells." (PMID 34218270, 2021).
gastric cancer (23 papers, 2017 to 2025). A primary or metastatic malignant neoplasm involving the stomach. "Specifically, we focused on two methylation sites, cg27492584 and cg14901671, and observed that their hypomethylation in stomach cancer samples is closely associated with the high expression of LINC00511." (PMID 40076759, 2025). "For example, LINC00511 functions as an apoptosis regulator in gastric cancer by binding with miRNAs." (PMID 40650307, 2025). "It has been experimentally found that the overexpression of LINC00511 promoted the proliferation, migration, and invasion of gastric cancer cells." (PMID 40076759, 2025). "For example, LINC00511 binds to miR-625-5p and accelerates proliferation and metastasis of gastric cancer." (PMID 36874361, 2023). "Apparently, the overexpressed LINC00511 is manifested in gastric cancer, and LINC00511 knockdown encumbers cell maturity and increases cell death ratio." (PMID 35477702, 2022). "We found that LINC00511 was highly expressed in gastric cancer and that this expression positively correlated with larger tumor size, advanced TNM stage and poor disease-free survival." (PMID 32042282, 2020). "LINC00511 is expected to be a prognostic marker for bladder metastasis in stomach cancer." (PMID 40076759, 2025). "Furthermore, LINC00511 overexpression enhances the proliferation of gastric cancer cells by functioning as a competing endogenous RNA (ceRNA) to regulate the miR-124-3p/PDK4 pathway." (PMID 38531930, 2024). "Finally, miR-625-5p/NFIX, miR-124-3p/EZH2, miR-625-5p/STAT3 and miR-29b/KDM2A are other molecular axes regulated by LINC00511 in gastric cancer." (PMID 37124625, 2023). "Moreover, LINC00511 functioned as an oncogene in non-small cell lung cancer, colon cancer, glioma, breast cancer, gastric cancer, and cervical cancer." (PMID 36874361, 2023). "Thus, we concluded that the down‐regulation of LINC00511 suppressed the progression of gastric cancer cells." (PMID 34427967, 2021). "Another study found that the high expression of LINC00511 could promote the proliferation and migration of gastric cancer cells." (PMID 34852705, 2021). "The functions of LINC00511 in gastric cancer progression were explored." (PMID 32042282, 2020). "LINC00511 expression was obviously higher in gastric cancer tissues." (PMID 32042282, 2020). "The functions of LINC00511 in gastric cancer are poorly understood." (PMID 32042282, 2020). "We also evaluated LINC00511 expression in 25 paired gastric cancer tissues." (PMID 32042282, 2020). "Our findings indicate that LINC00511 may be a novel therapeutic target for gastric cancer treatment." (PMID 32042282, 2020). "We established that LINC00511 may contribute to the proliferation and invasion of gastric cancer cells by modulating miR-515-5p, indicating that LINC00511 may be a potential molecular target for the development of anti-cancer drugs." (PMID 32042282, 2020). "LINC00511 expression was determined to examine its function in gastric cancer progression." (PMID 32042282, 2020). "Knockdown of LINC00511 significantly reduced growth of the xenograft of gastric cancer cells." (PMID 32042282, 2020). "We found that knockdown of LINC00511 could inhibit gastric cancer tumorigenesis through its sponging action on miR-515-5p." (PMID 32042282, 2020). "Moreover, the expression of LINC00511 negatively correlated with miR-515-5p in gastric cancer tissues." (PMID 32042282, 2020). "This study aimed to investigate the expression, biological function, and downstream mechanism of LINC00511 in gastric cancer (GC)." (PMID 34224294, 2021). "Therefore, LINC00511 might interact with miR-515-5p in gastric cancer progression." (PMID 32042282, 2020). "High LINC00511 expression levels correlated with bigger tumor size and advanced TNM stage in gastric cancer patients." (PMID 32042282, 2020). "LINC00511 is a tumor promoter that sponges miR-625-5p by targeting NFIX in gastric cancer cells and could be considered a brand new target for gastric cancer treatment." (PMID 34337069, 2021).
gastric cancer (continued). "Other studies have also shown that lncRNAs CERS6-AS1, LINC00511, PCED1B-AS1, LINC00649, NR2F1-AS1, AL139002.1, LINC00265, and MYLK-AS1 might promote the progression of gastric cancer and therefore, have the potential to be novel therapeutic targets for treating gastric cancer." (PMID 35089117, 2022).